MANSC1 (MANSC domain containing 1)
Synonyms: LOH12CR3; FLJ10298; 9130403P13Rik
Tractability: Antibody: UniProt predicts a signal peptide or a membrane-spanning region.
Gene: Protein-coding gene on chromosome 12 (12,326,056 to 12,350,483, reverse strand). Ensembl gene ENSG00000111261.
Subcellular location: Membrane
Subcellular location (Human Protein Atlas): Vesicles; Golgi apparatus
Gene Ontology:
Molecular function: protein binding
Cellular component: Golgi apparatus; membrane
Genetic constraint (gnomAD): Loss-of-function variants: 14 observed, 14.78 expected, observed/expected ratio (o/e) 0.95, 90% interval 0.62 to 1.48. The upper end of that interval is the gene's LOEUF score, 1.48, which puts it in group 6 of 6, group 1 being the genes least tolerant of losing a copy. Missense variants: 486 observed, 538.4 expected, observed/expected ratio (o/e) 0.9, 90% interval 0.84 to 0.97. Synonymous variants: 227 observed, 212.27 expected, observed/expected ratio (o/e) 1.07, 90% interval 0.96 to 1.19.
Homologues: Orthologues: chimpanzee MANSC1 (99% identical), macaque MANSC1 (93% identical), dog MANSC1 (67% identical), guinea pig MANSC1 (66% identical), rabbit MANSC1 (61% identical), mouse Mansc1 (61% identical), rat Mansc1 (60% identical), pig MANSC1 (59% identical), tropical clawed frog mansc1 (29% identical). Paralogues in human: C11orf24 (17% identical), MANSC4 (12% identical).
Diseases named in the same sentence as MANSC1 in open-access papers:
MANSC1 is named in the same sentence as 12 diseases in open-access papers, as found by Europe PMC text mining. Sharing a sentence is not in itself a finding about the gene and the disease. The quoted sentences say what the papers report.
prostate carcinoma (3 papers, 2013 to 2023). A carcinoma that arises from epithelial cells of the prostate gland. "Nucleotide mutation of MANSC1 protein may be associated with prostate cancer." (PMID 32751923, 2020). "A functional MANSC1 Single Nucleotide Polymorphism has been also identified in patients with overall prostate cancer and non-advanced prostate cancer in a genome-wide association study." (PMID 37228491, 2023).
chronic leukemia (1 paper, 2020). A slowly progressing leukemia characterized by a clonal (malignant) proliferation of maturing and mature myeloid cells or mature lymphocytes. "MANSC1 has been reported to be expressed in BM samples of most patients with acute and chronic leukemia and other hematological tumors." (PMID 32751923, 2020).
non-small cell lung carcinoma (1 paper, 2023). A group of at least three distinct histological types of lung cancer, including non-small cell squamous cell carcinoma, adenocarcinoma, and large cell carcinoma. "In contrast, an association between high expression of MANSC1 and a positive prognosis for overall survival was found in patients with non-small cell lung cancer." (PMID 37228491, 2023).
periodontitis (1 paper, 2022). An acute or chronic inflammatory process that affects the tissues that surround and support the teeth. "In periodontitis, MANSC1 was negatively correlated and the other four hub crosstalk genes (FMNL1, PLAUR, RNASE6, and TCIRG1) were positively correlated with five hub IRRGs, namely, AQP9, C5AR1, CD14, CSF3R, and PLAUR." (PMID 36545026, 2022). "MANSC1 was significantly negatively correlated with 4 hub cross-talk genes in periodontitis, and MANSC1 was significantly negatively correlated with 5 hub IRRGs." (PMID 36545026, 2022). "Additionally, RNASE6 was highly correlated with myeloid-derived suppressor cells (MDSCs) in periodontitis, and MANSC1 was highly correlated with plasmacytoid dendritic cells in PD." (PMID 36545026, 2022). "The main findings of the current study identified five hub crosstalk genes (i.e., FMNL1, MANSC1, PLAUR, RNASE6, and TCIRG1) to be the linking mechanisms between periodontitis and PD." (PMID 36545026, 2022). "Five genes (i.e., FMNL1, MANSC1, PLAUR, RNASE6, and TCIRG1) were identified as crosstalk biomarkers linking PD and periodontitis." (PMID 36545026, 2022).
MANSC1 also shares sentences with these, for which no sentence is quoted: acute myeloid leukemia (1 paper); breast carcinoma (1); cancer (1); diabetes (1); leukemia (1); myelodysplastic syndrome (1); primary myelofibrosis (1); tumor (1).